PAFAH1B1 (platelet activating factor acetylhydrolase 1b regulatory subunit 1)
Diseases named in the same sentence as PAFAH1B1 in open-access papers (continued):
Sharing a sentence is not in itself a finding about the gene and the disease.
myeloproliferative neoplasm (1 paper, 2015). A clonal hematopoietic stem cell disorder, characterized by proliferation in the bone marrow of one or more of the myeloid (i.e., granulocytic, erythroid, megakaryocytic, and mast cell) lineages. "Of note, the possible contribution of lowered expression of several of these genes in human tumors is already proven, like PAFAH1B1 in non-small cell lung cancer, SMARCC1 in pancreatic cancer and NKN2 in myeloproliferative neoplasm (MPN) precursors." (PMID 26113842, 2015).
necrotizing enterocolitis (1 paper, 2011). Necrotizing enterocolitis (NEC) is a devastating disease that affects mostly the intestine of premature infants. "Platelet-activating factor acetylhydrolase, isoform 1b, subunit 1 (Pafah1b1), another high-priority candidate, was implicated in susceptibility to necrotizing enterocolitis in humans, and Pafah1b1 deficiency in mice led to increased susceptibility to this disease." (PMID 22241984, 2011).
omphalocele (1 paper, 2025). Omphalocele is an embryopathy classified in the group of abdominal celosomias and is characterized by a large hernia of the abdominal wall, centered on the umbilical cord, in which the protruding viscera are protected by a sac. "While PAFAH1B1, YWHAE and CRK are associated with major phenotypes of 17p13.3, RTN4RL1 may be involved in white matter changes and HIC1 might contribute to the occurrence of omphalocele." (PMID 40390087, 2025). "The findings of this study indicate that PAFAH1B1, YWHAE and CRK are associated with major phenotypes of 17p13.3, and RTN4RL1 may be involved in white matter changes and HIC1 might contribute to the occurrence of omphalocele." (PMID 40390087, 2025).
osteoporosis (1 paper, 2025). A condition of reduced bone mass, with decreased cortical thickness and a decrease in the number and size of the trabeculae of cancellous bone (but normal chemical composition), resulting in increased fracture incidence. "Therefore, we can hypothesize that the severe osteoporosis and osteolysis observed in NGPS cells might be associated with an increased level or activity of LRRK1 and/or PAFAH1B1." (PMID 39956852, 2025).
tumor (12 papers, 2012 to 2025). "Interestingly, chromosome region 17p13.3 harboring PAFAH1B1 gene also demonstrated association with advanced tumor stage in array-CGH data." (PMID 22691236, 2012). "The results of GO analysis showed that the DEGs (CD74, PAFAH1B1) were associated with the biological process of the cytokine-mediated signaling pathway, suggesting that these two genes may have the potential to stimulate tumor growth and progression." (PMID 31998788, 2020). "In liver cancer, PAFAH1B1 mRNA is often downregulated and acts as a tumor suppressor, with its overexpression leading to reduced proliferation." (PMID 40378956, 2025). "Gene dosage of PAFAH1B1 and ZNF322A was significantly higher in tumor tissues than autopsy tissues from Caucasian." (PMID 22691236, 2012). "To further explore the selectivity of the effects of PAFAH1B1 suppression in tumor versus non-transformed cells, beyond the single cell line evaluated in the CRISPR screen, we transiently silenced PAFAH1B1 in two additional non-malignant cell lines (MCF10A and MCF12A)." (PMID 40378956, 2025).
cancer (11 papers, 2014 to 2025). A tumor composed of atypical neoplastic, often pleomorphic cells that invade other tissues. "However, increased PAFAH1B1 expression is also associated with malignant phenotypes in most cancer models studied, including glioblastoma, non-small cell lung cancer, leukemia, cholangiocarcinoma, and salivary gland carcinoma." (PMID 40378956, 2025). "Consistent with other cancer models, suppressing PAFAH1B1 in TNBC cells led to centrosome amplification as well as disorganized metaphase plates suggestive of multipolar spindles that are known to increase DNA damage during mitosis." (PMID 40378956, 2025). "Therefore, we used ONCOMINE online cancer database to analyze the mRNA expression of PAFAH1B1 and PAFAH1B2 in HCC and found that the mRNA expression of PAFAH1B1 and PAFAH1B2 was no significant changes in HCC." (PMID 34490100, 2021). "Interestingly, genetic manipulation of other dynein regulators elicits fewer or milder cell-cycle-related phenotypes in HeLa cells when compared to the effects of LIS1/PAFAH1B1 loss, suggesting that LIS1 may be more important for the mitotic functions of dynein, especially in cancer." (PMID 40378956, 2025). "We also analysed the effects of PAFAH1B1 and DCTN1 on OS in various cancers, and found that the high expression of these two genes is associated with poor prognosis of various cancers." (PMID 38466053, 2024). "Both PAFAH1B1 and DCTN1 are shown to promote cancer in specific cancers, while NDE1 has mutual binding properties with PAFAH1B1 and DCTN1, respectively." (PMID 38466053, 2024). "We finally obtained eight bona fide cancer driver genes, including CEP57, HNRNPL, KLF5, OXA1L, PAFAH1B1, RBM39, SYT13, and TFDP1." (PMID 31925297, 2020). "In addition, we noticed seven of them have been included in the latest version of The Network of Cancer Genes35 (KLF5, OXA1L, RBM39, and TFDP1) or CancerMine36 (HNRNPL, KLF5, PAFAH1B1, SYT13, TFDP1), two manually curated cancer gene databases, further confirming our findings." (PMID 31925297, 2020).
neurological disorders (6 papers, 2015 to 2024). "Finally, Pafah1b1 (targeted by Mir132), has been associated with the abnormal migration of cortical neurons and with neurologic disorder in mice and humans." (PMID 32093602, 2020).
infection (2 papers, 2021 to 2022). The state of being infected such as from the introduction of a foreign agent such as serum, vaccine, antigenic substance or organism. "Using qRT-PCR, we demonstrated that S. japonicum infection significantly increased expression of Prkab1, but not Ppp2ca, and Pafah1b1 in the livers of ND-fed mice compared with that in the control mice with infection." (PMID 33391522, 2021).
PAFAH1B1 also shares sentences with these, for which no sentence is quoted: schizophrenia (14 papers); Pachygyria (8); brain malformation (6); neurodevelopmental disorder (5); autism spectrum disorder (4); cholangiocarcinoma (4); Cognitive impairment (4); glioma (4); neuroblastoma (4); brain disorder (3); lung adenocarcinoma (3); polymicrogyria (3); tubulinopathies (3); bipolar disorder (2); colorectal cancer (2); degenerative diseases (2); Failure to thrive (2); Focal cortical dysplasia (2); glioblastoma (2); leukemia (2); liver cancer (2); mental disorder (2); psychosis (2); X-linked lissencephaly (2); acute lymphoblastic leukemia (1); albinism (1); behavioural disorders (1); Canavan disease (1); cardiomyopathy (1); Cerebellar hypoplasia (1).
A further 43 diseases each share a sentence with PAFAH1B1 in 1 paper.